ENSG00000285723 (novel protein)
Synonyms: LOC128706665
Gene: Protein-coding gene on chromosome 20 (10,413,708 to 10,434,222, reverse strand). Ensembl gene ENSG00000285723.
Homologues: Orthologues: mouse Gm56451 (67% identical).